INS (insulin)
Diseases named in the same sentence as INS in open-access papers (continued):
Sharing a sentence is not in itself a finding about the gene and the disease.
diabetes (continued). "Furthermore, the treatment of psoriasis with TNF-α inhibitors may also have beneficial effects on the development of atherosclerosis and components of the metabolic syndrome, such as improving endothelial function, reducing the risk of diabetes mellitus, and improving insulin sensitivity." (PMID 40584532, 2025). "Diabetes mellitus is a chronic metabolic disease characterized by hyperglycemia resulting from defects in insulin secretion, insulin action, or both." (PMID 40558453, 2025). "The timing of insulin administration, particularly for long-acting insulins like Gla-300, plays a critical role in diabetes management." (PMID 40190894, 2025). "These favorable changes contribute to improved insulin sensitivity and mitigation of diabetes-related liver dysfunction." (PMID 40806520, 2025). "Research has suggested a connection between miRNAs and insulin secretion and resistance, two major components in diabetes development and management." (PMID 40626241, 2025). "MicroRNAs are involved in the pathogenesis of diabetes mellitus by affecting pancreatic β-cell functions, INS resistance, or both." (PMID 41376825, 2025). "Optimal nutrition significantly influences blood glucose levels, insulin resistance, and type 2 diabetes mellitus management." (PMID 41516982, 2025). "These attributes drive their utility as high-affinity molecular tools in bioanalytics/chemical biology and clinically validated therapeutics (e.g., ziconotide for chronic pain and insulin for diabetes)." (PMID 41079656, 2025). "For instance, individuals with diabetes and coexisting depression frequently exhibit worse glycemic control, which is mediated by chronic stress and its downstream effects on insulin sensitivity." (PMID 40003660, 2025). "Diabetes is the most prevalent metabolic disease characterized by elevated levels of blood glucose due to an impaired ability of the body to produce or respond to insulin, and it primarily includes type 1 diabetes mellitus (T1DM) and T2DM." (PMID 40006605, 2025). "The use of the FSL system is effective for many different patient groups, including those receiving multiple daily insulin injections, pregnant women with diabetes, and the elderly with diabetes." (PMID 40161060, 2025). "A reduced PDX-1 expression in T2DM compared with that in non-diabetes because of DNA methylation from hyperglycemia impairs the islet response to insulin sensitivity and exacerbates glucose metabolism." (PMID 41189666, 2025). "Oxidative and inflammatory stress in the insulin-sensitive tissues also contributes to diabetes-related insulin resistance and tissue damage." (PMID 40806520, 2025). "The significant reductions in FBS, insulin levels, and insulin resistance highlight the potential of exercise as a key strategy for improving diabetes management." (PMID 40091956, 2025). "Type 2 diabetes mellitus is defined by the coexistence of two pathophysiological features: diminished insulin secretion and reduced sensitivity of target tissues to insulin, commonly referred to as insulin resistance." (PMID 40732323, 2025). "T2DM, a chronic metabolic disorder accounting for 90–95% of all diabetes cases, is characterized by insulin resistance and relative defects in insulin secretion." (PMID 41003141, 2025). "The cost of managing diabetes, for example, was US $237 billion in the United States in 2017, with insulin alone costing approximately US $5000 per user annually." (PMID 41289583, 2025). "Despite the availability of insulin therapy and glucose monitoring tools, in-hospital diabetes management remains a significant challenge." (PMID 40980547, 2025). "Among patients with diabetes, 60% were on oral medications, 6.2% on insulin alone, and 16.9% received a combination of treatments." (PMID 40313432, 2025).
diabetes (continued). "Based on the significant differences in metabolic biomarkers between ND-DKD and newly diagnosed type 2 diabetes mellitus patients, our study selected insulin, C-peptide, and lipoproteins to explore potential biomarkers for predicting DKD." (PMID 41140685, 2025). "Activating mutations in ABCC8, which encodes for the outer subunit of the ATP-sensitive potassium channel (K-ATP channel), result in the inability to release insulin, leading to a form of monogenic diabetes with autosomal dominant transmission." (PMID 40003320, 2025). "Multiple factors influence QoL in individuals with diabetes, including disease duration, treatment modality (especially insulin use), the presence of comorbid conditions, gender, educational level, and socioeconomic status." (PMID 41464418, 2025). "The dosage of insulin should be consistent and the patient's injection technique should be reviewed regularly by the diabetes team." (PMID 40226177, 2025). "A systematic search of five databases (PubMed, EMBASE, Cochrane, Web of Science, and CNKI) for RCTs investigating the effects of exercise interventions on insulin sensitivity in patients with diabetes was conducted." (PMID 40951419, 2025). "We should also note a growing field of human milk composition science, which has identified obesity- and diabetes-related biomarkers (leptin, insulin, and glucose) as predictors of breastfeeding cessation among mothers with obesity." (PMID 40691947, 2025). "Diabetes is a metabolic disorder characterized primarily by insufficient or impaired insulin secretion, leading to elevated blood glucose levels over an extended period." (PMID 41459066, 2025). "These discoveries highlight the AMPK/SIRT1/PGC‐1α system as a key controller of diabetes development, presenting new treatment possibilities that target insulin function, sugar processing, and fat regulation through precise pathway adjustments." (PMID 41268687, 2025). "The use of SIPs can improve confidence in managing daily injections, improve diabetes management, reduce missed bolus injections, and improve the ability to appropriately adjust insulin dosing." (PMID 40142601, 2025). "The most frequently prescribed biologics were insulin (glargine, aspart, and lispro) merely because diabetes is a common disease, with an estimated 11 million patients in Japan in 2021." (PMID 40770534, 2025). "Differentiating iPSCs into dopamine-producing neurons for PD treatment or insulin-producing beta cells for diabetes control depends on the exact control of culture conditions, growth factors, and signaling pathways." (PMID 40405306, 2025). "There is currently a paucity of research conducted in Ghana to assess adherence to insulin therapy among diabetes patients, with studies to date skewed towards assessing adherence to oral anti-diabetes medicines." (PMID 39854487, 2025). "SARS-CoV-2 alone can be an important catalyst for newly discovered diabetes by destroying (through infection) Β-cells and impairing their ability to produce insulin." (PMID 40729244, 2025). "Patients with type 1 diabetes and their families should visit a diabetes clinic to initiate insulin therapy." (PMID 40950999, 2025). "Hormonal changes after menopause, which impact body composition and insulin sensitivity, make this population more vulnerable to diabetes." (PMID 39834664, 2025). "An approach targeting multiple pathways (weight reduction, insulin sensitivity, inflammation, and cardiovascular risk) represents the future of OSA management in patients with diabetes." (PMID 41155523, 2025). "DPP-4 inhibitors significantly reduced daily insulin requirements, particularly bolus doses, and postprandial blood glucose (by −34.40 mg/dL), especially in patients with a BMI < 25 kg/m2 and diabetes duration <3 years." (PMID 41026724, 2025).
diabetes (continued). "Through a comprehensive analysis of predictive factors, including diabetes duration, HbA1c, C-peptide levels, and insulin use, this study highlights how patient-specific characteristics can influence remission outcomes." (PMID 40005466, 2025). "Coumarin derivatives were identified as potential treatments for diabetes and related complications due to their ability to repair pancreatic β-cells and improve insulin signaling." (PMID 40541990, 2025). "Patients showed a significantly higher prevalence of type 2 diabetes mellitus, hypertension, and dyslipidemia, which was reflected in elevated levels of glucose, insulin, triglycerides, and aminotransferases." (PMID 40943431, 2025). "The controlled release of insulin from natural polymers is a critical area of study for advancing drug delivery systems, especially in managing diabetes." (PMID 40352348, 2025). "This decline in insulin suggests impaired insulin production or function in the Ob/ObHFD mice, further reinforcing their utility as a model for studying diabetes." (PMID 40693271, 2025). "Cav-3 is closely involved in insulin signaling, glucose metabolism and lipid homeostasis, dysfunction of which are common manifestation of diabetes." (PMID 40012041, 2025). "Diabetes mellitus is a metabolic disease characterized by hyperglycemia with inadequate insulin secretion or resistance." (PMID 40926989, 2025). "Diabetes mellitus, a major metabolic disorder characterized by chronic hyperglycemia and insulin dysfunction, continues to pose a global health challenge." (PMID 41000259, 2025). "For example, in the case of metabolic diseases like diabetes, precise control over insulin release is essential." (PMID 40619603, 2025). "Regular exercise improves insulin sensitivity, glycemic control, and cardiovascular health, reinforcing its essential role in diabetes management." (PMID 41218056, 2025). "HSI is primarily influenced by body mass index, which decreased significantly over the study period, whereas NLFS is more dependent on insulin levels and the presence of diabetes mellitus—parameters that remained relatively stable." (PMID 40565353, 2025). "GSIS is one of the fundamental regulatory mechanisms of insulin exocytosis in the β-cell that presents a key pharmaceutical target in diabetes." (PMID 40014914, 2025). "By inhibiting pancreatic α-amylase, gedunin reduces glucose release from dietary starch and enhances insulin sensitivity, suggesting its utility in managing diabetes." (PMID 39861132, 2025). "Elevated LDH levels also reflect the severity of pancreatic necrosis and inflammation, which are related to pancreatic beta-cell dysfunction and increased insulin resistance, leading to diabetes." (PMID 41404504, 2025). "Monitoring for individuals in prestage 1 and stages 1–3 of T1D is determined by islet autoantibody status, glycemic status, diabetes-related symptoms, and insulin requirement." (PMID 40529832, 2025). "Thus, exploring associations between AAM and CRP, fasting insulin, and fasting glucose on a nationally representative sample with a wide age range of both pre- and postmenopausal women to elucidate possible pathways for the increased risk in diabetes in those with earlier AAM is warranted." (PMID 38912813, 2025). "An 80-year-old woman with type 1 diabetes mellitus was transferred to an Australian quaternary hospital with refractory hyperglycemia and diabetic ketoacidosis despite receiving >300 units of insulin daily." (PMID 40860576, 2025). "Chronic methadone treatment significantly reduced hyperglycemia and the incidence of diabetes and restored pancreatic insulin secretion in these mice, likely indicating the action of μ receptor agonism and increased insulin secretion from the pancreas." (PMID 40083398, 2025). "Prospective studies have also shown that people with diabetes using connected insulin pens and able to view their CGM have increased TIR and reduced TAR compared to users without access to CGM readings." (PMID 41039947, 2025).
diabetes (continued). "Diabetes mellitus is a global metabolic disorder characterised by chronic hyperglycaemia resulting from impaired insulin secretion, insulin action, or both." (PMID 40951416, 2025). "A larger proportion of Group A had diabetes for more than five years, 47 (33.6%) compared to Group B at 14 (10.0%), (p<0.001), and more frequent use of insulin and oral hypoglycemic agents (p=0.001)." (PMID 40666554, 2025). "In Akita mice, stimulation of β cell macroautophagy by rapamycin-mediated inhibition of mTOR prevented β cell apoptosis, increased pancreatic insulin content and ameliorated diabetes." (PMID 39996055, 2025). "The main source of contact is a diabetes educator, who has a scope of practice to monitor insulin and medication intake with limited capacity/time for education." (PMID 40724111, 2025). "Bisphenol A, an endocrine disruptor, has been shown to affect insulin sensitivity and glucose metabolism, potentially exacerbating diabetes‐related kidney damage." (PMID 41497483, 2025). "This is contrary to what has been observed in diabetic rats where no change in myostatin transcripts was observed with streptozotocin-induced diabetes or insulin treatment." (PMID 40575255, 2025). "Diabetes affects millions and is a significant contributor to kidney disease, while access to insulin and other treatments remain limited in many LMICs." (PMID 41343509, 2025). "Diabetes mellitus (DM) is a chronic metabolic disorder characterized by persistent hyperglycemia resulting from impaired insulin secretion, insufficient insulin production, or decreased insulin sensitivity." (PMID 40733621, 2025). "Some individuals with diabetes require multiple medications, including insulin, oral drugs, and other injectables." (PMID 40620800, 2025). "These methods showed high potential for diabetes therapy, offering robust hypoglycemic effects, enhanced glucose sensing, and controlled insulin delivery." (PMID 39433696, 2025). "Inadequate glycemic control in diabetes increases insulin levels, stimulates fat synthesis, inhibits lipolysis, and impairs the transformation of lipids into lipoproteins, which are essential for lipid transport from the liver." (PMID 40432897, 2025). "Currently, diabetes management strategies primarily focus on improving glycemic control and increasing tissue sensitivity to insulin, as well as preventing macro- and microvascular complications and reducing their severity." (PMID 39944202, 2025). "Type 2 diabetes mellitus (T2DM) is recognized as a metabolic syndrome, primarily marked by insufficient insulin caused by pancreatic β-cell dysfunction and insulin resistance in target organs." (PMID 39995417, 2025). "Most models studying or involving the evolution of diabetes have been built upon the model of Topp et all, which describes the long-term regulation of glucose and insulin with the simplest structure." (PMID 40568093, 2025). "Excessive fructose consumption is a significant driver of metabolic disorders, including obesity, diabetes, non-alcoholic fatty liver disease and non-alcoholic steatohepatitis primarily by promoting insulin resistance and fat accumulation." (PMID 40260383, 2025). "Beta:alpha cell ratio was significantly reduced in ‘high-fibrosis’ donors and all individuals with insulin-treated diabetes were in this subgroup." (PMID 40991018, 2025). "As expected, compared to Group 2, Group 3 were more likely to have type 1 diabetes (p = 0.024), longer duration of diabetes (t = 4.886, p < 0.001), higher HbA1C (t = 2.734, p = 0.008) and more likely to be on insulin (p = 0.001)." (PMID 41366327, 2025). "The vitamin D receptor (VDR) is expressed in insulin-responsive and immune cells, including pancreatic β-cells, adipocytes, skeletal muscle, and T lymphocytes, suggesting a potential regulatory role in diabetes pathophysiology." (PMID 40863099, 2025).
diabetes (continued). "Diabetes mellitus (DM) is a chronic metabolic disorder characterized by elevated blood glucose levels resulting from defects in insulin secretion, insulin action, or both." (PMID 40116715, 2025). "This reduces the concentration of glucose in the body and improves insulin secretion, which is effective in diabetes management." (PMID 40869372, 2025). "It is another step toward improving the quality of life, effectiveness, and safety of insulin therapy in people with diabetes." (PMID 41426796, 2025). "Glycemic management in diabetes patients remains heavily reliant on multiple daily insulin injections, which often leads to poor patient compliance and an elevated risk of hypoglycemia." (PMID 40292663, 2025). "Choosing the most reliable method to estimate glycoregulation is probably even more important than the mode of diabetes treatment (oral antidiabetic drugs and/or insulin)." (PMID 40430224, 2025). "Preoperative and postoperative diabetes medication (both oral and insulin) history was available for 122 PDAC patients." (PMID 40557340, 2025). "We observed elevated BiP AMPylation levels across multiple tissues and signature markers for diabetes including glucose intolerance and reduced serum insulin levels." (PMID 40073934, 2025). "Flavonoids in diabetes enhance insulin sensitivity, reduce resistance, and protect pancreatic β-cells from oxidative stress." (PMID 41368517, 2025). "Incidence of diabetes and pre-diabetes in groups of high and low beta-cell function, subdivided by small and large decrease in insulin sensitivity (DIS)." (PMID 41561051, 2025). "Daily insulin injections present a challenge for individuals managing diabetes, particularly those requiring long‐term basal insulin therapy." (PMID 40509887, 2025). "MOTS-c treatment delayed diabetes onset, improved glucose intolerance and reduced β-galpositive senescent β-cells in insulin-resistant mice." (PMID 40855115, 2025). "The two major types of diabetes are type 1 (T1DM, insulin deficiency) and type 2 (T2DM, insulin resistance) with individuals with T2DM frequently requiring treatment with insulin." (PMID 39937900, 2025). "This necessitates the possibilities for government subsidising and expanding access to the insulin therapy that aids in the overall control of glycaemia in patients with diabetes and therefore plays into reducing the prevalence of diabetes." (PMID 41155876, 2025). "Because this process has been known in much detail for a while, the presence of the C-peptide was used to test for endogenous insulin production for the diagnosis of diabetes." (PMID 39916408, 2025). "FBG is the most commonly used indicator for diabetes, reflecting the body’s insulin regulation function for blood glucose." (PMID 39925752, 2025). "Sleep quality, age, gender, diabetes duration, and insulin route significantly correlated with FOH (p < 0.05), while glycemic control and insulin use did not." (PMID 40357213, 2025). "Families and clinicians preferred in-person education because learning to use diabetes technology requires mastery of physical skills, such as placing a pump site and entering insulin delivery settings into the device." (PMID 41246816, 2025). "The current therapeutic interventions for diabetes primarily revolve around the exogenous administration of insulin, oral antidiabetic medications, modifications to one's lifestyle, and, recently, microbiota interventions." (PMID 40913218, 2025). "NEU3 has been reviewed for its involvement in obesity and diabetes, though its impact on insulin sensitivity and metabolic regulation remains controversial and context-dependent." (PMID 41301440, 2025). "People living with diabetes can revisit their glucose trends, dietary choices, and insulin patterns at any time, reinforcing lessons from structured TPE sessions and maintaining adherence as their condition evolves." (PMID 41282582, 2025).